MUC1 (mucin 1, cell surface associated)
Diseases named in the same sentence as MUC1 in open-access papers (continued):
Sharing a sentence is not in itself a finding about the gene and the disease.
tumor (continued). "MUC1 has also been suggested to function in epithelial morphogenesis and tumor progression due to its extensive expression in secretory epithelial tissues from mid-gestation throughout adulthood and elevated level of expression found in carcinomas and metastatic lesions." (PMID 30405607, 2018). "Recent studies shows that Galectin-3 secreted by tumor cells binds TF-antigen on MUC1." (PMID 29507546, 2018). "In particular, novel glycosylation patterns on proteins expressed by tumor cells may allow for the specific targeting of these cells, as in the case of the unique mucin 1 (MUC1) glycoepitopes that are highly expressed in a variety of cancers." (PMID 30740109, 2018). "The biocomplex was validated both in vitro and in vivo and demonstrated to be able to specifically deliver Dox and PTX in MCF-7 MUC1 positive cells and improved efficacy in reducing cell viability and in vivo tumor growth, when compared to similar biocomplexes loaded with single drugs." (PMID 30384431, 2018). "Furthermore, vaccination generated long term MUC1-specific antibody and T cell responses and delayed growth of MUC1+ve tumours in mice." (PMID 30200528, 2018). "It remains to be seen whether MUC1 is highly expressed on T cells in a tumor microenvironment and in conditions of persistent viral/bacterial infection like other T cell coinhibitory molecules." (PMID 30405607, 2018). "Importantly, in contrast to intracellular survivin, MUC1 is expressed on the surface of tumor cells and can be recognized by antibodies for antibody-mediated tumor destruction." (PMID 29415891, 2018). "Additionally, CA 15-3 tumor antigen is highly increased in patients with CTC clusters, possibly reflecting a higher tumor load but also tumors that are characterized by an elevated shedding of mucin 1 (MUC-1)-containing cells into the bloodstream." (PMID 30458879, 2018). "It seems plausible that increased aberrant MUC1 cell surface expression may render a tumor more immunogenic; however, whether this increased expression actually translates into improved response to immunotherapeutic approaches remains unknown." (PMID 30479696, 2018). "In the current study, we demonstrate that a tripartite branched CPP incorporating the H-2Kb (SAPDTRPAP)- and HLA-A2 (STAPPAHGV)-restricted CTL epitopes from the MUC1 tumour antigen with the universal Th epitope tetanus toxoid (tetCD4) is internalised into DC in vitro, as well as in vivo." (PMID 30200528, 2018). "By contrast, both IGHA1 and MUC1, known O‐linked glycoproteins, showed no detectable change between normal and tumor tissue indicating that the changes in O‐linked glycoproteins observed in tumor tissue are highly selective." (PMID 30459171, 2018). "Nevertheless, structural overview on anti-MUC1 antibodies and antibody targeting tumor-associated antigenic glycopeptides in general have not been mentioned." (PMID 29857542, 2018). "Taken together, hSiglec-9-hIg2 could suppress proliferation of MM46-MUC1 tumor cells and might be a candidate as a new therapeutic agent targeting MUC1." (PMID 29342882, 2018). "If several antigens are presented, interpretation regarding the contribution of MUC1 to effects on tumour growth, which may be documented, will be difficult." (PMID 29784646, 2018). "Moreover, the difference of glycosylation between tumor Muc1 and normal tissue Muc1 presents a nice distinction between tumor cells and normal cells." (PMID 29357376, 2018). "In this study, we employed bispecific antibody approach to target Muc1 positive tumor cells." (PMID 29357376, 2018). "In total, 60.6% of the tumor specimens had MUC1 expression in at least 11% of tumor cells." (PMID 29987260, 2018). "The nanoprobes, with or without aptamer functionalization, were intravenously injected into mice bearing tumors derived from two TNBC cell lines expressing MUC1 at a high and low extent, and the major tumor uptake was obtained by active targeting of MUC1 with a very low passive targeting." (PMID 30428522, 2018).
tumor (continued). "Furthermore, a variety of anti-MUC1 mAbs have been successfully radiolabeled and used for tumor imaging." (PMID 30428522, 2018). "Thereby, this design provides an efficient platform for MUC1 detection, may be a potential method for tumor diagnosis, bioanalysis, and clinical analysis." (PMID 35547495, 2018). "Additionally, bone marrow of Muc1−/− KO mice demonstrated an increased expression of CD11b+Gr1+ myeloid-derived suppressor cells (MDSCs), which are immune suppressive and support tumor progression." (PMID 30405607, 2018). "As shown e.g. for MUC1 and other over-expressed self-antigens, central tolerance can be incomplete or absent for self-peptides that are associated with tumours due to over-expression, tissue- or germline-specific expression." (PMID 30254248, 2018). "Regarding the role of MUC1 in NSCLC, several clinical studies have demonstrated a negative prognostic association of tumor MUC1 overexpression in NSCLC." (PMID 30479696, 2018). "The MUC1 Abs might further aid in the control of tumor dissemination and identify better clinical outcomes of BC patients." (PMID 29568299, 2018). "This specificity of our anti-hMUC1 monoclonal antibody could be because it recognizes different posttranslational modifications of MUC1 in normal versus tumor tissue." (PMID 29987260, 2018). "Results indicate that optimization of the MUC1 antigen cross-processing could be induced upon tumor derived MVsMUC1 internalization in clinical grade X-DCs, despite their acidic phagosomal compartment, that is a feature of macrophage cells." (PMID 30455687, 2018). "The combined use of MUC1 glycopeptides with other tumor antigens currently in clinical tests, might further increase the sensitivity and specificity for early cancer detection." (PMID 29857542, 2018). "Therefore, it was expected that an agent inhibiting the binding of Siglec-9 to MUC1 interfered the transmission of immunosuppressive signal, leading to provide anti-tumor potential to the animals bearing MUC1-expressing tumors." (PMID 29342882, 2018). "This enhanced cellular internalization and accumulation of T-NPs over NPs is most likely due to the specific binding of TAB004 to tumor form of MUC1 expressed on BxPC3.MUC1 cells thus enabling the NPs to readily internalize through a process of macropinocytosis." (PMID 29685122, 2018). "However, in a tumor microenvironment, MUC1 loses its O-glycan branching and dissociates from its C-terminus domain, which is attached by hydrogen bonding." (PMID 29651637, 2018). "We have recently shown that uptake of tumor-derived MVs exerts an immunostimulatory effect on antigen presentation by DCs, inducing a faster alkalinization of phagosomal compartment thus allowing cross-presentation of the MUC1 tumor glycosylated antigen." (PMID 30455687, 2018). "Mucin 1 (MUC1), being an oncogene, is an attractive target in tumor immunotherapy." (PMID 29558459, 2018). "Therefore, based on leads from human cancer studies, we have identified autoantibodies to CMYC and MUC1 in canine tumours." (PMID 30361548, 2018). "Over 80% of PDA expresses this tumor form of MUC1 and is an established target for immunotherapy." (PMID 29685122, 2018). "As a broadly expressed tumor antigen, Muc1 presents as an ideal target for tumor therapy." (PMID 29357376, 2018). "The MUC1 tumor glycoantigen was a molecular cargo component of the MVsMUC1 as characterized by flow cytometry and Western blot analysis confirmed the presence of the MUC1 antigen." (PMID 30455687, 2018). "In vivo tumour targeting monitored by fluorescence imaging has been also achieved using a NIR fluorescent dye-labelled MUC1 aptamer, in which one end of a PEG spacer has been linked to the NIR fluorescent hydrophilic cyanine dye and the other coupled to the aptamer." (PMID 29261171, 2017).
tumor (continued). "Furthermore, subgroup analysis stratified by nationality, cancer type, adjuvant therapy, sample size, methods, cut-off value, MUC subtype, tumor location, antibody for MUC1 and antibody for MUC4 were performed respectively." (PMID 29221212, 2017). "Thus, we propose that the MUC1-induced pro-inflammatory cytokines expression in IECs attracts inflammatory cells, especially mononuclear cells, from the venous system to the tumor site." (PMID 29285251, 2017). "Moreover, co-administration of the inhibitors of MUC1–EGFR–ABCB1 with paclitaxel significantly blocked not only tumor growth but also relapse in xenograft mouse model." (PMID 28796259, 2017). "When stratified by sample type, a significant risk was found in the sera group (HR=2.38, 95% CI: 1.47–3.82, P < 0.001), indicating that MUC1 may be a convenient tumor marker for use in clinical practice." (PMID 29163831, 2017). "However, all samples from low to high-grade adenocarcinoma revealed strong expression of tumor form of MUC1, phopsho-p65 and EzH2." (PMID 29285251, 2017). "Focusing on one of the most aggressive CTC type, which from the primitive tumor spreads to the CNS, we documented that CSF floating cancer cells overexpress syndecan-1, MUC-1 and, in a proportion of cases, the putative stem-cell markers CD15, CD24, CD44, and CD133 in BCLM." (PMID 28399903, 2017). "MUC1 immunohistochemical expression increased during progression to EA and followed tumor invasion." (PMID 28212575, 2017). "DF3 for MUC1 may be a more tumor-specific antibody in immunohistochemistry than others (i.e. VU4H5) in HNC especially for paraffin-embedded tissues, as the same to 8G7 for MUC4." (PMID 29221212, 2017). "MUC1 is present on the surface of the tumor cells, close to the growth factors surrounding it." (PMID 29250208, 2017). "Overexpression of MUC1 in clinically tumor free tissue thus could play a dual role in cancer development." (PMID 28038473, 2017). "Sialylated MUC1 was predominantly localized on the bile canalicular surface of tumor cells." (PMID 28325920, 2017). "Furthermore, MUC1-sensitized T-cells preferentially lysed partially histocompatible MUC1-expressing tumor targets." (PMID 27974697, 2017). "Moreover, the tumor form MUC1-ST, though the engagement of Siglec-9, induces macrophage differentiation to a TAM-like phenotype." (PMID 29285251, 2017). "Indeed, binding of gal-3 to poly-N-acetyllactosamine residue of cell surface mucin (MUC1) attenuated the interaction of tumor cells with NK cells, leading to tumor cell evasion from NK cell immunity." (PMID 29258258, 2017). "Therefore, MUC1 extracellular domain was responsible for the severe chronic inflammation and higher tumor incidence detected in our MUC1.Tg mice subject to CAC." (PMID 29285251, 2017). "We have previously shown that the tumor-associated MUC1 is cross-processed by DCs when the glycoantigen is carried by MVs, not when MUC1 tumor-associated glycoprotein is internalized as soluble molecule." (PMID 28993771, 2017). "In CRC, tumor MPs such as MUC1-, ACE- and CA19-9 bearing MPs, were significantly less observed in case of thrombo embolic event (0, 0 and 0 MPs/ μL respectively) than without (15 [0–6673] MPs/ μL, p=0.02; 20 [0–1850] MPs/ μL, p=0.002; and 21 [0–4337] MPs/ μL, p=0.0009, respectively)." (PMID 29228619, 2017). "Six radiation-treated surviving mice, including two cured mice and 4 mice still bearing tumors, developed tumors in their left flank upon challenge with Renca-MUC1 cells, showing that radiation alone did not cause anti-tumor immunity." (PMID 28116088, 2017). "We have now investigated whether tumor irradiation augments a specific immune response to MUC1 TAA antigen." (PMID 28116088, 2017). "In case of tumour specific markers–MUC1/Y and SNCG, mRNA expression was elevated in culture, suggesting that analysed tissue samples were constituting heterogeneous populations, with high percentage of normal, non-neoplastic cells, which were negatively selected during culture course." (PMID 27803125, 2016).
tumor (continued). "These anti-MUC1 antibodies were able to recognize MUC1 expressing MCF-7 tumor cells." (PMID 27472370, 2016). "In addition to cytomorphological analysis, gene expression of tumor associated genes (Cytokeratin-18, Cytokeratin-19, Cytokeratin-20, Cytokeratin-7, EPCAM, MUC1, HER2, EGFR) and of leukocyte markers (e.g. CD45, CD68) was tested in enriched CTC fractions." (PMID 25862542, 2016). "While EGF-receptor expression was almost abrogated in the SW-13 tumor model (1.2 ± 0.2%; p < 0.001 vs. MUC-1) a significant higher expression was detectable in MUC-1 tumors (100 ± 0%) compared with all other tumor models (NCI-H295R: 44.5 ± 4.1% and SJACC-3: 45.9 ± 4.9%; both p < 0.001vs." (PMID 27764813, 2016). "The activation of upstream signaling cascades by MUC1 can have significant impacts on the activation and regulation of downstream transcription factors resulting in reprogramming of gene expression profiles to favor tumor progression." (PMID 27483328, 2016). "Expression of both MUC16 and MUC1 has also been shown to dampen the Toll-like receptor mediated immune response at ocular surfaces, and may play a role in tumor progression." (PMID 27483328, 2016). "The recombinant virus used in fowlpox-TRICOM expresses three costimulatory transgenes, B7.1 (CD80), Intercellular Adhesion Molecule 1 (ICAM-1), and lymphocyte function-associated antigen 3 (LFA-3), plus one or more tumor-associated antigens, such as Carcinoembryonic antigen (CEA) and MUC-1." (PMID 27669306, 2016). "However, in the recurrent tumor population 8/13 tumors have either histological subtype, indicating that MUC1 is indeed expressed at the highest level in metastatic lesions." (PMID 27618037, 2016). "In addition to these tumor and matched normal sections we also stained a larger series of normal tissues known to express MUC1, including kidney, larynx, uterus, stomach, small intestine, and salivary gland." (PMID 27545199, 2016). "The exact mechanism by which the tumor form of MUC1 modifies the tumor microenvironment is still unknown." (PMID 27754373, 2016). "We hypothesized that incomplete immunological memory would be evidenced by outgrowth of tumor with down regulated MUC1 and MHC molecules." (PMID 26788922, 2016). "Similarly, only vaccination with rotating lysates resulted in T-cell recognition of every tested syngeneic MUC1+ tumor digest." (PMID 26788922, 2016). "While the antibodies we describe here do not internalize, they could still be used to deliver a therapeutic load to tumor cells, owing to their exquisite specificity for tumor MUC1." (PMID 27545199, 2016). "Jude Children's Research Hospital, Memphis, Tennessee) for providing the SJ-ACC3 tumor model and Guillaume Assie and Jérôme Bertherat (INSERM U1016, Institut Cochin, Paris, France) for providing the information about the mutational status of MUC-1." (PMID 27764813, 2016). "In addition, hypoglycosylated MUC1 can inhibit its own processing by DC as a tumor antigen and presentation to T cells, thereby preventing anti-tumor immune responses." (PMID 27754373, 2016). "We examined whether such immunoediting would persist phenotypically if selection pressure of the anti-MUC1 response was removed by culturing the Panc02.MUC1 tumor ex vivo." (PMID 26788922, 2016). "Moreover, Dox-loaded Apt-Td induced a significantly higher cytotoxicity to MUC1-positive cancer cells versus MUC1-negative control cells, indicating that Apt-Td achieved targeted drug delivery to MUC1-positive tumor cells in vitro." (PMID 27203221, 2016). "There is some indication that MUC1 expression is involved in tumor progression as well." (PMID 27190429, 2016). "This pattern of immunogenic modulation was observed against a broad range of tumor-associated antigens, such as CEA, MUC1, PSA, and brachyury, and associated with augmented expression of multiple proteins involved in antigen processing and tumor immune recognition." (PMID 26862729, 2016).
tumor (continued). "Epithelial-to-mesenchymal transition (EMT) is the critical process for tumor metastasis, and could be suppressed by inhibiting mucin-1 (MUC1) glycosylation." (PMID 27276675, 2016). "A key observation was that vaccination even with minimalist antigens such as non-glycosylated 9mers produced CD8+ as well as CD4+ T-cell repertoires that recognized both non-glycosylated and glycosylated peptides as well as tumor-associated MUC1." (PMID 26788922, 2016). "Finally, solamargine increased phosphorylation of AMPKα, while inhibiting MUC1, p65 and tumor growth were observed in vivo." (PMID 27830724, 2016). "This can explain the inflammatory role of MUC1 and its activity in tumor promotion and progression." (PMID 27754373, 2016). "Our first attempts on the construction and characterization of MUC1 CAR T cells using variable regions of five of the antibodies, showed that they could be activated by MUC1 peptide to produce IFNγ, and lyse tumor cells." (PMID 27545199, 2016). "This all affects development of stronger anti-MUC1 immunity that could otherwise target the abnormal MUC1 as an antigen on tumor cells for efficient cancer immunosurveillance." (PMID 27754373, 2016). "In order to determine whether the primary prostate and breast cultures in fact retained the characteristics of tumour cells, mRNA expression of MUC1/Y was measured." (PMID 27803125, 2016). "The extrahepatic pancreatobiliary immunohistochemical profile is characterized by expression of a considerable number of markers, including cytokeratins (CK7, CK17, and CK19), mucins (MUC1 and MUC5AC), and tumor-associated epithelial markers (CA19-9, monoclonal CEA, CA125, and maspin)." (PMID 27829047, 2016). "Winn assays further demonstrated that lysate-sensitized T-cells from hyperimmunized MUC1.Tg mice were as ineffective as naïve T-cells for controlling directly admixed MUC1+ tumor challenges, even though the MUC1-hyperimmune T-cells provoked down regulation of tumor MUC1 and H-2Kb." (PMID 26788922, 2016). "MUC-1 tumor analysis revealed highly vascularized, proliferating and SF-1 positive xenografts." (PMID 27764813, 2016). "Hence, while MUC1 expression appears to be related to tumor stage, its impact on survival remains controversial." (PMID 27298226, 2016). "In tumor cells MUC1 promotes tumor growth, metastasis, and drug resistance, and the C-terminal tail may serve as an oncogenic signaling molecule." (PMID 27669306, 2016). "The TIME trial is a randomized, double-blind, placebo-controlled Phase 2b/3 trial that enrolls previously untreated patients with stage 4 NSCLC without a known activating EGFR mutation and with MUC-1 expression in at least 50 % of tumor cells." (PMID 27532018, 2016). "MUC1 is a shared tumor antigen expressed on >80% of human cancers." (PMID 27545199, 2016). "This may be an impediment to developing DNA or viral MUC1 vaccines intended to produce cellular anti-tumor responses." (PMID 27472370, 2016). "This tumor form of MUC1 is considered a viable target for cancer immunotherapy." (PMID 27754373, 2016). "An advantage of using endogenous MUC1 CD4+ and CD8+ epitopes was that the T cells generated could be re-stimulated at the site of the tumor by endogenous MUC1 peptides for cytokine production and CTL activity." (PMID 27472370, 2016). "As MUC1 is a widely expressed tumor antigen, found on about 75% of tumors that kill, effective vaccine strategies with optimal peptides will have widespread applicability, especially as combined appropriately with immunomodulatory therapies such as checkpoint inhibitors." (PMID 27367740, 2016). "Many questions remain as to how best to deploy MUC1 as a tumor vaccine." (PMID 26788922, 2016). "Furthermore, MUC1 and MUC4 hypomethylation status is statistically associated with development of distant metastasis, tumor stage and overall survival for PDAC (stage IIA and IIB) patients." (PMID 27283771, 2016).